CD4 (CD4 molecule)
Diseases named in the same sentence as CD4 in open-access papers (continued):
Sharing a sentence is not in itself a finding about the gene and the disease.
AIDS (continued). "Besides, independent of CD4 and viral load counts, anemia has been reported to predict HIV progression to acquired immune deficiency syndrome (AIDS) with poor survival; on the other hand, treatment of anemia was observed to be associated with reversal of increased risk of death." (PMID 26045966, 2015). "In our analysis, we found that people who failed to achieve a CD4 count above the level present at the time of starting a new regimen, despite having achieved and maintained viral suppression <50 copies/mL on ART, tended to have an increased risk of developing non-AIDS morbidity and mortality." (PMID 24498036, 2014). "Furthermore, while Nef-mediated CD4 downregulation is typically maintained or enhanced throughout the HIV-1 disease course, Nef’s HLA-I downregulation activity appears to be maintained in chronic infection, but is reported to diminish after progression to AIDS." (PMID 24041011, 2013). "Additionally, nearly half of the HIV co-infected patients were not receiving ART at the time of MDR-TB treatment initiation, despite the fact that pulmonary TB is a criteria for initiating ART in the clinical staging of HIV/AIDS (irrespective of CD4 cell count)." (PMID 22629356, 2012). "One advantage of the method is that if alternative methods are developed to select people for treatment – e.g. relying on viral load or some new type of clinical observation, rather than CD4 count – these could also be described in terms of years of AIDS-related mortality that we seek to avert." (PMID 22943377, 2012). "Given the frequent association of either Env-specific CD4+ or CD8+ T-cell responses with progression to AIDS, it is possible to speculate that an Env-based T-cell immunogen may not provide protection against AIDS progression." (PMID 23028895, 2012). "Thus, if the outcomes of HIV/AIDS programs in resource-limited settings are to be improved, all individuals testing positive for HIV must receive continuous pre-ART care that includes regular CD4 counts to ensure that ART is initiated as soon as they become eligible for treatment." (PMID 21811403, 2011). "However, the CD4 cell slope did not significantly affect the progression to AIDS or death when the analysis was restricted to 1,731 patients with CD4 >350 cells/μl at baseline (hazard ratio 0.99, 95% CI 0.94–1.03, for each 10 cells/μl per year reduction in CD4 cell decline)." (PMID 20186270, 2010). "As lower baseline CD4 count correlates to worse prognosis, decreasing the treatment threshold and expanding treatment coverage may be an urgent next step in China to control both AIDS and non-AIDS related mortality and morbidity." (PMID 20500898, 2010). "However, irrespective of therapy eras, within each CD4/viral load stratum, low, moderate and high GRG status conveyed a step-wise increase in AIDS risk, which was also evident among subjects with the lowest risk CD4 cell count (≥700 cells/mm3) and viral load (<20,000 copies/ml) profile." (PMID 18776933, 2008). "Host factors (and potentially other unknown factors) can affect rates of disease progression independently of viral load; it is possible that existing variation in progression rates to AIDS or death in the MACS is not reflected in the viral load or CD4 cell count data we examined." (PMID 18253479, 2008). "However, two of the participating states had laboratory reporting of at least some CD4 counts and viral loads at the time of the study and the third had an established, clinically-based HIV reporting system that had been in place and integrated with AIDS surveillance for 10 years." (PMID 17850671, 2007). "However neither CD4-cell count or AIDS diagnosis, were available in either study." (PMID 16579856, 2006). "In addition, it has been suggested that antiretroviral drugs might have effects on risk of AIDS and/or death, which are not mediated by their effect on HIV-RNA and CD4 cell count." (PMID 17183720, 2006).
AIDS (continued). "This article presents two cases of patients with AIDS secondary to uncontrolled HIV who were admitted with fever, malaise, low CD4 + counts, and a history of noncompliance with antiretroviral therapy (ART)." (PMID 40276474, 2025). "AIDS, or advanced HIV disease, is defined by a CD4 cell count <200/microL or the presence of any AIDS-defining condition regardless of CD4 cell count." (PMID 39958093, 2025). "HIV-specific factors, including duration of diagnosis, AIDS stage, HIV-RNA levels, CD4 count, duration and ART regimen, did not significantly influence the likelihood of a 5-year cardiovascular risk exceeding 5%." (PMID 40870513, 2025). "ART was initiated early, prior to significant CD4 T cell decline, with participants remaining stable for at least 12 months on their initial ART, and none exhibiting AIDS-defining illness or comorbidities typically seen in adults with HIV." (PMID 40862746, 2025). "LTNP was defined as reaching age 8 years without disease progression (defined as an AIDS diagnosis or immunosuppression based on WHO immunosuppression-for-age thresholds, age-adjusted CD4+z-scores or CD4+ counts)." (PMID 39912745, 2025). "Two key informants mentioned that most laboratory tests were not free, except for CD4 and viral load tests, and many HIV/AIDS patients faced financial difficulties in affording these tests." (PMID 40589828, 2025). "Bloodwork for CD4 T-lymphocyte percentage and/or count was drawn during hospital admission for 328 (21.6%) PWH including 182 PWH with AIDS and 146 PWH without AIDS." (PMID 39067055, 2025). "A negative AIDS status likely correlated with effective ART and HIV viral suppression because ART would preserve CD4 T-lymphocyte count and prevent AIDS-defined illness in most PWH." (PMID 39067055, 2025). "Chronic management of HIV/AIDS is one of the priority strategies, which includes providing ART to all HIV-positive people in care and treatment clinics (CTCs) regardless of CD4 count and WHO HIV/AIDS staging." (PMID 38481731, 2024). "HAND patients displayed more frequently non-CNS AIDS-defining conditions, lower nadir CD4+ T cells and increased CD4+ T-cell exhaustion (lower CD4+CD127+ and CD4+CD45RA+ T-cell percentages), in comparison to individuals without cognitive impairment." (PMID 38704619, 2024). "Meanwhile, studies failed to establish a clear correlation between CD4+ T-cell responses against HIV and protection from AIDS, probably as a consequence of assessing the immune responses during chronic infection." (PMID 38932264, 2024). "Although no specific dietary pattern has been found to increase CD4+ T cell counts, dietary changes can lower inflammation levels and slow the progression of HIV/AIDS." (PMID 39802299, 2024). "We applied a definition of LTNP to include children without an AIDS-defining illness, no ART, or no more than one CD4 count below 500 cells/ml (or CD4% ≤25%) for 10 years since infection meeting our criteria." (PMID 38036259, 2024). "Nevertheless, HIV-1 viruses using the CCR5 co-receptor, characteristic of the early stages of infection, do not downmodulate CD4, differently from viruses entering through CXCR4 or CXCR4/CCR5, which are common during AIDS." (PMID 38787201, 2024). "Idiopathic CD4 lymphocytopenia (ICL) is a rare condition where CD4 T cell counts are low, similar to advanced human immunodeficiency virus (HIV) infection but without acquired immunodeficiency syndrome (AIDS)-related symptoms." (PMID 38665729, 2024). "Meanwhile, the Department of Health and Human Services (DHHS) and the European AIDS Clinical Society (EACS) guidelines also recommend that clinicians should initiate ART immediately, regardless of the baseline CD4 cell count." (PMID 38778273, 2024). "The negative correlation between levels of activated CD4 + CD38 + HLA-DR + T cells and BMI in ART-naïve PLWH is consistent with this immune marker and wasting occurring with progression to AIDS." (PMID 38310301, 2024).
AIDS (continued). "According to the guideline of comprehensive HIV/AIDS management, ART should be initiated early for all HIV-positive adults irrespective of their WHO clinical stages and CD4 cell count." (PMID 38085717, 2023). "The main risk factors for AIDS-defining neoplasms are the absence of antiretroviral therapy, reduced CD4+T lymphocyte count, detectable HIV viral load, and previous AIDS diagnosis." (PMID 37341221, 2023). "The Thai National AIDS programme (NAP) treatment guidelines have recommended rapid antiretroviral therapy (ART) initiation, regardless of CD4 count since 2014." (PMID 36943729, 2023). "Elevated in subjects with with a previous diagnosis of AIDS.Positive correlation between CSF cf-mtDNA with better neurocognitive performance, MCP-1, TNF-α, IL-8.Negative correlation with CD4+ T-cell nadir." (PMID 37762464, 2023). "CMVR was preponderant in AIDS patients with the following characteristics: white and non-Hispanic, homosexual, HIV RNA load ≥ 400 copies/mL, and CD4+ T-cells <50 cells/μL." (PMID 37305416, 2023). "The latest Guidelines, published in December 2018, suggested no matter their count of CD4+T cells at baseline, all people living with HIV/AIDS should receive ART." (PMID 37679721, 2023). "Although CXCR4 expression on CD4+ T cells does not vary during AIDS, CCR5 expression is increased compared to HIV-infected non-AIDS individuals." (PMID 38420260, 2023). "We define late presentation as a CD4 cell count below 350 cells/mm3 at the time of HIV diagnosis, or presenting with an AIDS-defining illness regardless of CD4 count." (PMID 37351535, 2023). "Thus, it is plausible that the elevated levels of EVs bearing PD-L1 in serum from pre-AIDS-NHL cases in this study could be derived from PD-L1 expressing B-cells or Bregs, which could be a response to systemically suppress the immune system to inhibit HIV-infected CD4+ T-cells." (PMID 37809067, 2023). "It is not uncommon to see a short-term weight gain in HIV/AIDS patients who begin ART, particularly in those with a pretreatment low body mass index (BMI) and significantly low CD4 at the time of treatment." (PMID 35603131, 2022). "Lower CD4+ cell counts at HAART initiation compared with CD4 cell counts at the initial HIV diagnosis in Korea suggest that a worse immune status in people treated with HAART might explain the higher mortality due to AIDS compared with individuals who were never HAART users." (PMID 36142061, 2022). "The differences in CD4 and CD8 T cells proportion remained statistically significant after excluding patients with AIDS from non-sarcoidosis patients." (PMID 35425769, 2022). "We added the analysis to compare the CD4 changes between the HIV positive, AIDS with AIDS defining symptoms and AIDS without AIDS defining symptoms." (PMID 36584083, 2022). "Using AIDS and HIV diagnoses data, including self‐reported time since the last negative test and laboratory results of CD4 cell count at diagnosis, we estimated HIV incidence in each population over 1975–2020 by modelling a cubic M‐spline." (PMID 36050916, 2022). "We found that the low CD4+ T cell counts significantly correlated with infection with Cryptosporidium spp., E. histolytica, and B. hominis but not with E. bieneusi in HIV/AIDS and MSM HIV/AIDS populations." (PMID 36067140, 2022). "According to the Guideline of HIV/AIDS Treatment and Care issued by the Ministry of Health of Vietnam, all people living with HIV/AIDS are eligible for receiving free ART services, regardless of their CD4 cell count or clinical stage." (PMID 33557412, 2021). "In TB patients co-infected with HIV/AIDS, antiretroviral therapy (ART) is also necessary regardless of CD4+ T lymphocyte count." (PMID 35222560, 2021). "Individuals admitted for infectious diseases were particularly likely to have unfavourable HIV-related clinical characteristics (low CD4, viral non-suppression, not on antiretroviral therapy (ART), previous AIDS)." (PMID 33926373, 2021).
AIDS (continued). "For instance, long term non-progressors can maintain high CD4 count, and control the virus for up to 10 years without ART, compared to “rapid progressors” who develop full blown AIDS within 3-4 years of infection." (PMID 34017334, 2021). "The male patient, 38-year-old, was previously diagnosed with HIV without AIDS as confirmed by negative molecular diagnosis for HIV infection and normal levels of T CD4+ and CD8+ lymphocytes both before and after the infection with SARS-CoV-2." (PMID 34901074, 2021). "Serious non-AIDS disease events (SNAE) are experienced disproportionately by immunologic non-responders (INRs), HIV-infected individuals who do not restore CD4 T cells in blood despite effective viral suppression." (PMID 34320023, 2021). "The clinical symptoms and signs of PCP were not typical; with decreasing CD4+ T cell counts, PCP infection in HIV/AIDS patients increased." (PMID 32911508, 2020). "In fact, in our study, markers of T-cell senescence (low TRECs and short TL) were similar in pHIVy and npHIVy and correlated only with CD4+ cells, regardless of HIV duration, coinfections or past AIDS events." (PMID 32572110, 2020). "In its 2014 Country Operational Plan for Zimbabwe, the U.S. President’s Emergency Plan for AIDS Relief (PEPFAR) program contributed $740,000 towards CD4 testing, whereas in subsequent years, CD4 testing has not been part of the PEPFAR portfolio." (PMID 32584821, 2020). "Effects of covariates; Age, Gender, VL baseline (VLBL), CD4 baseline (CD4BL), Non-adherence to treatment (NA) on HIV/AIDS progression defined by the time-dependent variables CD4 levels or viral load levels is assessed in this section." (PMID 30770728, 2019). "LTNPs are patients who do not progress to AIDS over an extended period, and they have a total or partial control of HIV replication, high CD4+ lymphocyte numbers, and absence of clinical symptoms." (PMID 30841566, 2019). "HIV/AIDS chronic care is one of the prioritized strategies which include providing of ART for every HIV positive individual irrespective of their CD4 count and WHO HIV/AIDS staging in order to make these people live longer with improved quality of life." (PMID 31428472, 2019). "Despite policies for universal HIV testing and treatment (UTT) regardless of CD4 count, there are still 1.8 million new HIV infections and 1 million AIDS-related deaths annually." (PMID 31060607, 2019). "European and Spanish guidelines now recommend initiation of ART in PLWH irrespective of CD4 count, given that early ART initiation has been found in clinical research studies to reduce serious AIDS events, non-AIDS events, and HIV transmission." (PMID 30395635, 2018). "He achieved excellent control of his HIV infection, with a pre-transplant CD4+ cell count of 950 cells/μL, CD4+:CD8+ ratio of 0.69, no detectable viral load, and no history of AIDS-defining illnesses." (PMID 30326889, 2018). "The association between sCD163 and frailty was independent of age, current CD4+ T-cell count, co-infection with HBV or HCV, a history of AIDS, or CD4:CD8 ratio (OR, 7.5; CI 1.4–39.7, p = 0.02)." (PMID 28754302, 2017). "Efforts should be made to ensure that the CD4 counts of people living with HIV and AIDS do not continue to fall after initiation into care in order to preserve psychomotor function." (PMID 27608675, 2016). "Other clinical markers including CD4 cell count, self-reported HIV symptoms, and AIDS diagnosis were not statistically different." (PMID 27313441, 2016). "Although effective ART has greatly reduced AIDS-related events in the majority of HIV-infected patients, normalization of CD8 counts is seldom observed even with optimal CD4 recovery." (PMID 26945343, 2016). "This also applies to Estonia, where the current guidelines from the European AIDS Clinical Society are followed and persons living with HIV are treated irrespective of their CD4+ T-cell count." (PMID 27813471, 2016).
AIDS (continued). "Studies investigating the relationship between intestinal parasitic infections and CD4+ T cell counts and diarrhea in HIV/AIDS patients with or without antiretroviral therapy in the region are not readily available hence the need to perform this study." (PMID 26754404, 2016). "TE can be inaugural of AIDS in patients who are not aware of their HIV seropositivity, but poor compliance with cotrimoxazole prophylaxis in patients with CD4 cell counts <200/μL is the major event leading to TE." (PMID 27355620, 2016). "Nonetheless lower CD4 count and lack of HIV-1 viral suppression at ten years after starting ART, and AIDS before or during the first decade of ART, were strong predictors of death during the second decade of ART." (PMID 27525413, 2016). "Eighteen patients did not have a documented CD4 count or known AIDS-defining illness, and thus were combined with the HIV+ but non-AIDS patients." (PMID 26265965, 2015). "Thailand recently revised its National Guidelines on HIV/AIDS Treatment and Prevention to recommend treatment for all people living with HIV (PLHIV), regardless of CD4 count." (PMID 26198342, 2015). "Our study also showed that the median CD4 count of the patients who were voluntarily tested and diagnosed [338 /μL (IQR 211–467)] was higher than that of patients with AIDS [54 /μL (IQR 23–98)] and non-AIDS diseases [234 /μL (IQR 122–392)]." (PMID 26606382, 2015). "Although HIV-2 can cause an immunodeficiency syndrome indistinguishable from HIV-1-induced AIDS, many HIV-2-infected individuals do not develop immunodeficiency within their lifetime and retain stable CD4 lymphocyte counts for many years." (PMID 24803534, 2014). "Characteristics of patients who had stored plasma were not different from those did not have it for age, CD4 cell count, HIV-RNA level, AIDS defining events and for prescribed antiretroviral therapy." (PMID 24589015, 2014). "The viral load pre-cART; the frequency of pre-cART AIDS diagnosis (CD4 < 200 cells/mL); and the frequency of subjects with an immunologic non-responder (INR) status (CD4 < 350 cells/mL) were also not significantly different (data not shown)." (PMID 24819230, 2014). "They include four clinical factors: the presence of another opportunistic disease, the presence of another non-AIDS related comorbidity, not receiving CPT, and not receiving ART; and one biological factor: having a CD4 cell count <50/mm3." (PMID 25506830, 2014). "Although no one in the sample had AIDS, the HIV disease burden was still substantial, with 47% of men and 37% of women having a CD4 cell count below 350, and 25% of men and 16% of women having WHO Stage 3 disease." (PMID 24886474, 2014). "We did not observe any effect of CD4+ cell counts and HAART on the occurrence of cryptosporidiosis in HIV/AIDS patients in this study." (PMID 24743521, 2014). "Non-anergic participants at HI had smaller, non-significant CD4 gains than those who were anergic after adjusting for CD4 at HI, race or ethnicity, gender, initial HAART regimen, and prior AIDS diagnosis." (PMID 24499779, 2014). "There was a persistent role of CD4 count at baseline and 12 months after starting ART in predicting rates of death from AIDS, non-AIDS infection, and non-AIDS malignancy." (PMID 24771333, 2014). "and I. belli, were significantly higher in HIV/AIDS patients who were not enrolled in ART when compared with those enrolled in ART and with CD4+ T-cell count >200 cells/μL." (PMID 23991132, 2013). "This methodology can be useful to determine the number of CD4 in places where there is no easy access to flow cytometry, reducing costs in determining the state of patients with HIV/AIDS." (PMID 24034560, 2013). "The CD4 count of MSM patients tended to be higher, and MSM were less likely to present with AIDS than non-MSM, although HIV viral load of MSM was significantly higher than that of non-MSM." (PMID 24339982, 2013).